CBFA2T3 (CBFA2/RUNX1 partner transcriptional co-repressor 3)
Diseases named in the same sentence as CBFA2T3 in open-access papers (continued):
Sharing a sentence is not in itself a finding about the gene and the disease.
Ewing sarcoma (1 paper, 2025). A small round cell tumor that lacks morphologic, immunohistochemical, and electron microscopic evidence of neuroectodermal differentiation. "We report a case of a girl with isolated extramedullary CBFA2T3::GLIS2-positive AMKL relapse, which was misdiagnosed as secondary Ewing sarcoma." (PMID 40565358, 2025). "Additional cytogenetic and molecular studies confirmed the presence of the CBFA2T3::GLIS2 fusion, but no Ewing sarcoma-specific EWSR1, FUS and CIC fusion transcripts were found." (PMID 40565358, 2025).
Insulin resistance (1 paper, 2024). Increased resistance towards insulin, that is, diminished effectiveness of insulin in reducing blood glucose levels. "Glucose tolerance test and insulin tolerance test data showed that insulin resistance is increased in Cbfa2t3−/− mice compared to Cbfa2t3+/+ mice." (PMID 38786053, 2024).
Sepsis (1 paper, 2025). Sepsis is defined as life-threatening organ dysfunction caused by a dysregulated host response to infection. "Only a small number of host genes were differentially expressed between the Gram-positive (HLA-B, SERPINB10, LOC105377885, CEACAM6, NIPA2) and Gram-negative (CBFA2T3, LOC107987303, MARCO) sepsis samples in our cohort." (PMID 40965975, 2025).
thyroid carcinoma (1 paper, 2020). "The elevated expression of CBFA2T3 was consistently associated with a better OS or DFS in 10 cancer types, including CHOL, COAD, HNSC, kidney chromophobe (KICH), brain lower-grade glioma (LGG), LIHC, LUAD, SARC, thyroid carcinoma (THCA), and THYM." (PMID 32774369, 2020).
tumor (22 papers, 2004 to 2025). "Variants in 5 genes (RPN1, CDKN2A, HRAS, PALB2, CBFA2T3) have been identified in 32 individuals with tumor from the extended cohort and classified as pathogenic, likely pathogenic, and VUS." (PMID 36845707, 2023). "RNA-seq analysis of the tumor biopsy material confirmed the expression of the CBFA2T3::GLIS2 fusion transcript, with its sequence fully matching that obtained in the initial RNA-seq results." (PMID 40565358, 2025). "For example, Cbfa2t3 was identified as downregulated in STHSC:MA9 versus progenitor-derived tumours, and in human AML, low expression of CBFA2T3 was associated with poor prognosis." (PMID 27397025, 2016). "Here, we demonstrate that the miR-27a/miR-27a* pair play pro-metastatic roles in OS cells that is mediated, at least in part, by targeting CBFA2T3, a putative tumor suppressor." (PMID 25749032, 2015). "Our results provide evidence, for the first time, that CBFA2T3 acts as a tumor suppressor in OS development and progression and can be post-transcriptionally regulated by the pro-metastatic MIR-27a gene." (PMID 25749032, 2015). "We demonstrated that CBFA2T3 is downregulated in majority of OS samples and its over expression significantly attenuated OS metastatic process mediated by miR-27a/miR-27a* underscoring CBFA2T3 functions as a tumor suppressor in OS." (PMID 25749032, 2015). "We also for the first time provide evidence that CBFA2T3 acts as a tumor suppressor in OS cells suggesting that deregulated CBFA2T3 expression by miR-27a and miR-27a*, at least in part, is accountable for their pro-metastatic action in OS." (PMID 25749032, 2015). "Remarkably, two individual tumors harbored a bi-allelic integration near the transcription start site of Cbfa2t3, suggesting functional inactivation of this candidate tumor suppressor gene." (PMID 20052266, 2010). "All these tumours had a slightly lower transcription of CBFA2T3 (a TSG)." (PMID 37393582, 2023). "Then, we investigated the expression of KLRG1 and CBFA2T3 in different tumor stages." (PMID 35265614, 2022). "Our findings, which suggest that CBFA2T3 expression is regulated by both miR-27a and miR-27a* as well as tumor suppressive properties of CBFA2T3 in OS cells, provide an insight in possible mechanisms underlying the pro-metastatic function of miR-27a in OS cells." (PMID 25749032, 2015). "Based on our data suggesting that CBFA2T3 is a potential target of miR-27a and miR-27a* and the fact that CBFA2T3 is genetically altered and/or has tumor suppressive properties in different cancer types, we decided to address a possible tumor suppressive role of CBFA2T3 in osteosarcomagenesis." (PMID 25749032, 2015). "In order to directly address the question whether CBFA2T3 functions as a tumor suppressor in OS, HOS, LM7 and SAOS2 cells were transduced with a lentivirus, which carries myc-tagged CBFA2T3." (PMID 25749032, 2015). "Overall, our data indicate that CBFA2T3 has a tumor suppressive, anti-metastatic role in OS cells and regulation of CBFA2T3 expression by miR-27a and miR-27a* might be accountable for the pro-metastatic action of these miRNAs." (PMID 25749032, 2015). "Hence, CBFA2T3 can potentially be used as a tumor antigen in future mRNA vaccines." (PMID 35265614, 2022). "Indeed, we provide evidence that the CBFA2T3 gene behaves as a tumor suppressor in OS." (PMID 25749032, 2015). "Overall, we identified two tumor antigens in LUAD - KLRG1 and CBFA2T3 - that could be used to develop mRNA vaccines." (PMID 35265614, 2022). "Possible candidates CBFA2T3, TERF2 and TERF2IP, FBXL8 and LRRC29 and FANCA were studied for insertion and deletion mutations and for expression differences using quantitative RT-PCR in a panel of tumour cell lines and primary tumours with and without loss of 16q." (PMID 16280054, 2005).
cancer (20 papers, 2012 to 2025). A tumor composed of atypical neoplastic, often pleomorphic cells that invade other tissues. "Different RUNX1 translocations have been described in various hematological malignancies, the RUNX1T3/CBFA2T3 fusion being the fifth most frequent partner in cancer-associated RUNX1 rearrangements." (PMID 38443661, 2024). "Although small, these differences affected important signaling pathways (NGF-stimulated transcription, IL-10 signaling, PERK activity) and cancer genes (CBFA2T3, ETV4, FGFR1, GLI1, SGK1, and STAT3)." (PMID 38968069, 2024). "These suggest that RAP1A, STARD13, SASH1, RECK, and CBFA2T3 had big positive network effects on down-expression of genes in stage-3 cancer." (PMID 33580150, 2021). "Among these genes, two are oncogenes and also translocated cancer genes (CBFA2T3 and PRDM16)." (PMID 33711952, 2021). "Of the oncogenes, three are translocated cancer genes (CBFA2T3, PDGFB and PRDM16)." (PMID 33711952, 2021). "Similarly, CBFA2T3 (chromosome 16) has documented roles in cancer biology as a transcriptional repressor, but again, there is no obvious role in vascular biology." (PMID 31801372, 2020). "In addition, previous studies have shown that several TSGs had significantly higher methylation levels in cancer, such as CBFA2T3 and TMEM25." (PMID 32774369, 2020). "Although CBFA2T3 deficient mice do not develop malignancies themselves it is possible that CBFA2T3 deficiency facilitates development and changes aggressiveness of different types of cancer." (PMID 25749032, 2015). "At stage 3, STARD13, CBFA2T3, RECK, and SASH1 had strong accordant/discordant effects on expression of genes in cancer, while APC, EXT1, NBL, KLK10, and PTCH1 had very weak accordant/discordant impacts on expression of genes in cancer." (PMID 33580150, 2021). "Hence, the strong TS genes SASH1, STARD13, RECK, CBFA2T3, RASSF2, RAP1A, and ARHGEF12 can be used as specific biomarkers for diagnosis of NSCLC cancer." (PMID 33580150, 2021). "CBFA2T3 and XPNPEP2 were downregulated in 15 and 10 TCGA cancer types." (PMID 32774369, 2020).
hematological malignancies (3 papers, 2013 to 2024). "First, it is well known that alteration of each protein, RUNX1 and CBFA2T3, separately, causes hematological malignancies." (PMID 33743795, 2021).
genetic diseases (1 paper, 2019). "The remaining genes, DPP6, INPP5F, CCHCR1, and CBFA2T3, are also associated with many genetic diseases." (PMID 31332212, 2019).
hematological cancer (1 paper, 2022). "Analysis by LC-MS/MS identified more than 600 Lmo2-interacting molecules in physiological LPs, including the previously reported components of Lmo2 complexes in hematological cancer cell lines, Lyl1, Tal1, Ldb1, Tcf12, Tcf3, and Cbfa2t3 (also known as ETO2 or MTG16)." (PMID 36126774, 2022).
CBFA2T3 also shares sentences with these, for which no sentence is quoted: colitis (2 papers); colon cancer (2); colorectal cancer (2); acute promyelocytic leukemia (1); adenoma (1); colon (1); colon dysplasia (1); Crohn's colitis (1); ductal carcinomas (1); endometrial adenocarcinoma (1); Familial adenomatous polyposis (1); infectious disease (1); lymphoma (1); megakaryoblastic leukemia (1); melanoma (1); myeloid leukemia (1); nephronophthisis (1); prostate carcinoma (1); sarcoma (1); thyroid neoplasm (1); Wilms tumor (1).